CD4 (CD4 molecule)
Diseases named in the same sentence as CD4 in open-access papers (continued):
Sharing a sentence is not in itself a finding about the gene and the disease.
infection (continued). "Despite the expanded contribution of antibody and CD8 T cells in secondary protective immunity, CD4 Th1 cells are still thought to be the primary cell type involved in the resolution of secondary infection." (PMID 25071779, 2014). "We demonstrate that the block to infection in macrophages is sensitive to CD4 cell surface levels using Affinofile cells." (PMID 24656066, 2014). "At this point, virus has usually integrated into long-lived resting CD4+ T cells and a persistent infection has been established." (PMID 24884551, 2014). "Infection of CD4+ cells by primate lentiviruses results in a rapid and constant down-modulation of cell surface CD4 expression level." (PMID 24822052, 2014). "Potential extrinsic factors include other immune cells, such as antigen-presenting cells (APCs) and B cells, which interact bidirectionally with CD4+ T cells to shape the response to infection." (PMID 25051576, 2014). "After 60 days, flow cytometric analysis of transgenic T cells found that approximately 25% of memory CD44+IL-7R+ CD4+ T cells were lost in untreated mice compared to drug-treated mice which had cleared the infection." (PMID 24904561, 2014). "We studied the turnover of SIV DNA resting CD4+ T cells during active infection in a cohort of 20 SIV-infected pigtail macaques." (PMID 24710023, 2014). "CD4+ T cells are critical immune effector cells, and alteration in their function can have grave consequences on responses to primary infection and the acquisition of immunity." (PMID 25051576, 2014). "A smaller proportion of IFNγ+CD44highCD4+ medLN Th1 cells was detected in Cd28flox/floxOx40cre/+ mice at 7 days post infection, just after the reported peak of CD4+ T cell expansion." (PMID 25347065, 2014). "The elevation of CSF NFL during PHI was not sustained at abnormal levels, and regressed to normal levels in those with chronic infection and higher blood CD4+ cells before again increasing with more advanced infection." (PMID 25541953, 2014). "IL-10+ regulatory B (Bregs), CD4+Foxp3+ regulatory T (Tregs), and CD4+CXCR5+Foxp3+ follicular regulatory T (TFR) cells regulate the progression of infection disease." (PMID 25199644, 2014). "Accumulating data suggest that CD4+ T-cell depletion following infection, as well as persistent immune activation, can partially explain this low and/or slow CD4+ T-cell recovery." (PMID 25293882, 2014). "Studies with HCV-infected patients have revealed that during the acute phase of infection, strong and long-lasting HCV-specific CD4+ and CD8+ T cell responses are associated with viral clearance." (PMID 24465502, 2014). "During the latent phase of the infection, CD4 T cell responses promote the expansion of antiviral CD8 T cells." (PMID 25120535, 2014). "Even with the relatively low precursor frequency prior to challenge, Th17 cells in mice vaccinated with split-flu antigen plus CRX-601were rapidly recruited and expanded to >5% of the CD4+ T-cells in the lungs at 5 days post infection." (PMID 24465206, 2014). "Within total T cells, significantly less CD4+CD8− T cells were present in the re-infection group than in the infection group." (PMID 25252649, 2014). "We found that low and high dose infections preferentially induced proliferation and cytokine production by CD8+ and CD4+ T cells, respectively, during early and late stages of infections." (PMID 25412267, 2014). "Co-administration of Ad-GMCSF at the time of vaccination appeared to have an effect on infection of CD4+ and CD8+ cells with PPRV." (PMID 24568545, 2014). "Our study complements those observations by demonstrating that there is indeed increased flux through the glycolytic pathway in primary CD4+ T cells upon infection with HIV-1." (PMID 25421745, 2014). "In C57BL/6 mice, TMEV infection results in rapid expansion of effector CD4+ and CD8+ T cells, which are efficient in clearing the virus." (PMID 25391297, 2014).
infection (continued). "In order to cope with these tasks, the CD4+ T-cell response has to adapt to the changing scenarios presented as the infection evolves." (PMID 25628621, 2014). "Further studies are also required to understand the role of CD8+ and CD4+ T cell responses to primary infection and disease development." (PMID 25375883, 2014). "Ex vivo infection of CASE1 CD4+ T cell blasts with HIV-1 R5BaL or X4LAI/IIIB strains resulted in virus replication, although at lower levels compared to those observed after infection of CD4+ T cell blasts from her partner." (PMID 25477316, 2014). "Regardless of the membrane with which virus fuses, entry via this mode of infection is dependent on the expression of CD4 and CCR5, as demonstrated by our inhibitor analyses." (PMID 25467409, 2014). "Is it the failure of CD4+ T helper cells that ultimately leads to the failure of the humoral immune response, and thus the failure to control the infection?" (PMID 25426115, 2014). "CD4+ T-cells are targets for infection by human immunodeficiency virus type 1 (HIV-1), whereby latent, replication-competent provirus can persist despite suppressive antiretroviral therapies." (PMID 25387392, 2014). "CD4+ T-cells have been shown to play a central role in immune control of infection with Plasmodium parasites." (PMID 25628621, 2014). "Abundance of CD4+ T cells allows rampant viral replication resulting in millions of viral particles per ml of plasma at peak viremia, occurring ∼21–28 days post infection." (PMID 24996694, 2014). "Viremic Non-Progressors (VNPs) are infrequent among HIV-infected individuals and remain clinically asymptomatic and maintain high CD4+ T cell counts despite many years of infection with robust virus replication." (PMID 25167059, 2014). "During infection with the intracellular parasite Toxoplasma gondii, the presentation of parasite-derived antigens to CD4+ and CD8+ T cells is essential for long-term resistance to this pathogen." (PMID 24722202, 2014). "Given the role of preexisting CD4+ T-cell immunity in limiting disease severity, this ethnic bias would place indigenous population vulnerable to infection in the wake of H7N9 pandemic." (PMID 24609014, 2014). "B lymphocytes and CD4 T cells numbers reached 800 cells/mg of lung tissue by 3 days post-infection with CD8 cell numbers being consistently lower." (PMID 24847941, 2014). "Annually, about 2.3 million people become newly infected with HIV, the virus that causes AIDS by gradually destroying CD4 cells and other immune system cells, thereby leaving HIV-infected individuals susceptible to other serious infections." (PMID 25513807, 2014). "This demonstrates that CD28 expression is required after T cell priming for intact effector CD4+ T cell responses during infection." (PMID 25347065, 2014). "This picture is now being challenged by the discovery of a more complex pattern of CD4+ T-helper cell subsets that appear during infection, including Tregs, Th17, Tfh, and more recently, Th22, Th9, and ThGM." (PMID 25360134, 2014). "IL-16 can be expressed by epithelial cells under inflammatory conditions and serves to chemoattract monocyptes/macrophages and CD4+ T cells to the infection site." (PMID 24465869, 2014). "During the acute phase of infection, IL-10 correlated positively with viral load and negatively with CD4+T cell counts." (PMID 24695530, 2014). "Others have demonstrated that with early infection of GALT with ART given four hours after infection, there is protection against rapid depletion of CD4+ T cells, yet SIV RNA and DNA were detected." (PMID 25502752, 2014). "CD4+ memory T-cells are a major target for infection by HIV-1, whereby latent provirus can establish and endure suppressive antiretroviral therapies." (PMID 25387392, 2014).
infection (continued). "More recently, a study compared the ability of wild-type mice and B cell-deficient mice to clear C. trachomatis genital infection, and demonstrated that CD4+ T cell immunity was essential for protective immunity to secondary infection." (PMID 25386180, 2014). "When incubated with both Vi10 and the Env-specific nAbs, infection of the CD4+CCR5+ GHOST cells by rVSV-EnvG4-G6IN was completely inhibited (compare row 2, columns 1, 3, and 4)." (PMID 25215861, 2014). "While TSCM were susceptible to infection by both R5 and X4 C-HIV viruses, the proportion of infected CD4+ T-cells that were TSCM was higher for R5 strains." (PMID 25387392, 2014). "We demonstrate here that SseB is also a target of CD4 T-cell immunity, generating a substantial response after experimental infection in human volunteers, with around 0·1% of the peripheral repertoire responding to it." (PMID 24891088, 2014). "Even if T-cell mediated CD4+/CD8+ response eventually participates in the control of the infection, the onset of a CD4+ response against Mtb is slow." (PMID 25000410, 2014). "Infection initiates naive CD4+ T cells to differentiate into phenotypically and functionally distinct subsets, although the precise subset depends on particular pathogen-derived and tissue-specific cues." (PMID 25051576, 2014). "In HIV and HAV infection, exosomes are required for trans-infection of CD4+ T cells and are likely to promote virus spread within the liver, respectively." (PMID 24905011, 2014). "To determine if the accumulation of PD-L2+ AAM from CX3CR1-GFP+ monocytes was CD4+ T cell dependent, we depleted CD4+ T cells from 5.5 to 6.5 weeks post-infection and analyzed PD-L2 expression on CX3CR1-GFP+ cells from the liver." (PMID 24967715, 2014). "We can sustain a specific immunological feature of patients studied, patients in the special condition of incapacity defense to infection, sometimes extreme (77.09% of the patients had a CD4 count below 100/μL)." (PMID 25408764, 2014). "TLR-mediated cytokine secretion by plasmacytoid DCs attracts CD4+ T target cells to the site of infection." (PMID 24782340, 2014). "We assessed sensitivity to receptor and fusion inhibitors as a way to examine if the envelopes from the various stages of infection had differences in their fusion capacity or ability to use low levels of CD4 and CCR5." (PMID 25430652, 2014). "As a result of glycosylation of gp120, macrophages and dendritic cells lose their ability to recognize and present processed antigen to the CD4+ T cells to significant level, resulting in inefficient transfer of infection to the CD4+ T cells." (PMID 26056579, 2014). "Recent findings have supported the impression that, although HIV is virtually able to infect any CD4+ T cell, there is a preference for the infection of activated lymphocytes." (PMID 25313360, 2014). "Most patients with VL have antigen specific CD4 T cells capable of secreting IFNγ both in the blood and at the site of infection - the spleen." (PMID 25275531, 2014). "Infection dependent polyclonal CD4+CD62L− T cells from mice with a chronic primary infection have been shown to mediate protection following adoptive transfer and needle challenge." (PMID 25473946, 2014). "Here, we have compared gene expression profiles of a human CD4+ T cell line at 24 h after infection with a cell line of the same origin permanently releasing SIVmac." (PMID 25163480, 2014). "CD4 T cells play a central role in immune responses to infection as well as acting in a regulatory role for maintaining homeostasis." (PMID 24586481, 2014). "CD8+ memory T cells remain in the epidermis close to the initial site of infection and migrate at a slower rate (2–3 μm/min) than dermis-localized CD4+ T memory cells (5–6 μm/min)." (PMID 25120547, 2014).
infection (continued). "We demonstrated that mice lacking 5-LO signaling displayed high susceptibility to L. infantum infection because of a commitment on the related Th17 axis released by CD4 T lymphocytes and neutrophil migration to the infection foci." (PMID 25309905, 2014). "We demonstrate that depletion of AM prior to infection also results in reduced total numbers of CD4 and CD8 T cells in the BAL of CL-treated mice as compared to PBS control mice." (PMID 24608125, 2014). "The results presented here demonstrate that continued CD28 signaling is required following T cell activation for an effective primary CD4+ T cell response to infection." (PMID 25347065, 2014). "A major obstacle to achieving a cure stems from the fact that HIV not only infects and kills cells involved in combating infection (CD4 T cells), but also establishes a stable reservoir in these cells that goes undetected by the immune system." (PMID 24662607, 2014). "After Ad5hr infection RM develop weak and variable hexon-specific CD4+ and CD8+ T cell responses in the blood." (PMID 25203111, 2014). "U87.CD4.CXCR4.CCR5 cells express CD4, CCR5 and CXCR4 and are susceptible to infection by all investigated virus strains." (PMID 25499264, 2014). "SIV reverse transcription was thereby blocked in inactivated CD4+ T-cells; the initial burst of virus replication was prevented and the vaccinated macaques were protected from a challenge infection." (PMID 25071760, 2014). "As one method of determining if inflammasome activation required infection, we blocked CD4, which is required for receptor-mediated HIV infection, prior to culturing monocytes with HIV virions." (PMID 24788318, 2014). "The invasion and infection of CD4+ T lymphocytes by human immunodeficiency virus type 1 (HIV-1) is a complex process involving many cellular events that have been the subject of many studies." (PMID 25105875, 2014). "Of the remaining 5 vaccinees, 3 (AG291, AH776, M770F) did not experience any loss of CD4+ T cell during the acute, post-acute and chronic phase of infection, maintaining CD4+ T cell counts comparable to the baseline values (range 1,104−2,309 cells/mmc)." (PMID 25356594, 2014). "N. gonorrhoeae activates TLR2 on CD4 T-cells, thus facilitating the infection, even at an earlier phase of the viral cycle, immediately after infection." (PMID 25313360, 2014). "For S142N, the ability to use CCR5 efficiently also enhanced its infectivity at any given level of CD4; thus, the overall level of infection across the entire matrix of CD4/CCR5 expression is higher." (PMID 24957778, 2014). "Infected DCs both expressed elevated IL-10 and were able to promote IL-10 expression in CD4 T cells, which constituted the largest population of IL-10-expressing cells in Cl13 infection at all time points observed." (PMID 24613988, 2014). "There are disparate models of the initial cell type of infection during male-to-female transmission, with some studies implicating CD4 T cells, others implicating Langerhans cells, while others report mixed pools of target cells." (PMID 25299616, 2014). "The key findings we described in CD4-depleted animals - high viral load, expansion of pro-inflammatory monocyte, increased level of sCD163, and massive infection of tissue-resident macrophages/myeloid cells – are all potential markers of CNS infection." (PMID 25356757, 2014). "Both groups were comparable in terms of age, sex, duration of infection, CD4 cell count, HIV viremia, (SCA) HIV DNA levels, CCR5 tropism and markers of activation at baseline." (PMID 25320633, 2014). "Six naïve Chinese macaques were infected with SIVmac239 and the status of infection, plasma viral load, and CD4+ T cell number confirmed that a classic SIV infection had been established." (PMID 25759828, 2014). "The increase of CD4+T cells was only observed in the late infection with both viruses (14 days p.i.)." (PMID 24725777, 2014).
infection (continued). "In this study, we showed that the absence of IFN-γ leads to a partial but not absolute block in CD8+ T cells recruitment to the site of infection, consistent with the survival curve obtained from the CD4+ T cell transfer from IFN-γ−/− to PtprcL3X mice." (PMID 24068938, 2013). "We also performed genistein pre-treatment plus one-dose post-infection treatment of resting CD4 T cells, and observed complete inhibition of HIV at all concentrations tested (2.5 to 40 μM) in one donor." (PMID 23782904, 2013). "This involves CD4 T cells working to eliminate the infection, but our understanding of the adaptive immune response is not complete." (PMID 24220507, 2013). "In contrast, in RL5, a rabbit CD4+ T cell line, infection with either vMyx-M029KO or vMyx-M029ID viruses were abortive compared to the control vMyx-GFP replication." (PMID 23853588, 2013). "Previous studies have suggested that the inhibition of productive infection with HIV-1 by Prostratin was mediated by the down-regulation of HIV-1 receptors CD4, CCR5 and CXCR4." (PMID 23201205, 2013). "Studies of escape have also been used in other imaginative ways - for example, to estimate the turnover of integrated DNA in resting CD4+ T cells, which is one of the blocks in the elimination of infection." (PMID 24020860, 2013). "Cells were obtained 5 weeks after infection of RAG+CD4+CD8 or RAG+CD8 mice, and were stained for CD107a expression directly ex vivo." (PMID 23874205, 2013). "Our data thus provide important new information on how IL-27 regulates CD4+ T cell responses during infection." (PMID 23593003, 2013). "In RAG+CD4+CD8 mice analysis of CD107a expression showed a small percentage of degranulating CD8+ T cells at the infection site." (PMID 23874205, 2013). "On these cells, HIV-1 attachment is mostly mediated by HSPGs, and this interaction was found necessary for successful infection when a low level of CD4 is expressed at the cell surface." (PMID 24312095, 2013). "We observed that TGFβ signalling in CD4+ T-cells is triggered early during T. muris infection, and antibody-mediated blockade of TGFβ function significantly protects mice from infection." (PMID 24098124, 2013). "Ag85B is strongly recognized by mouse Th1 cells, and frequently by human CD4+ T cells, during infection with MTB." (PMID 23637771, 2013). "There is evidence that the CD4+ T helper (Th)-1 response mediated by Interferon (IFN)-γ is protective against infection in vitro and in vivo." (PMID 23776551, 2013). "The intimate interaction in lymph nodes of APC with follicular CD4+ T cells points to these being major targets for trans infection." (PMID 24278768, 2013). "It was of interest to allow the LAINeffs∆-1 and LAINeffs∆-13 infections to continue past eight weeks to determine if these viruses would slowly deplete CD4+ T cells from blood." (PMID 24172637, 2013). "Here, we evaluate the role of the cortical actin in cell-to-cell transfer of virus antigens and infection of target CD4+ T cells." (PMID 24244453, 2013). "In the absence of treatment, 24% of the activated CD4+ T cells were actively infected by HIV as determined by GFP expression by flow cytometry, whereas infection of CD4+ T cells treated with 5′pppRNA supernatants was reduced to 11%." (PMID 23633948, 2013). "HIV-1-induced apoptosis appears to play an important role in depletion of CD4+ T-cells, decreasing immune responses to infection and facilitating viral persistence and increased viral loads and transmission rates." (PMID 23658782, 2013). "We measured the depletion of peripheral CD4 T cells after infection with m3KOΔnef in all seven animals." (PMID 23785211, 2013). "There is a complexity in how CD4+ T cells relate to trans infection based on their tissue location and activated, inflammatory state, which has received little attention." (PMID 24278768, 2013).